APC (APC regulator of Wnt signaling pathway)
Diseases named in the same sentence as APC in open-access papers (continued):
Sharing a sentence is not in itself a finding about the gene and the disease.
tumor (continued). "Of the three broad phases that encompass CRC tumour evolution, the initiating or ‘breakthrough’ phase is often triggered by truncating mutations to APC, providing cells with a growth advantage that progress to small adenomas in the colon." (PMID 29570681, 2018). "Activation of cGMP signaling, thereby promoting epithelial homeostasis and restoring its tumor suppressive function represents an enticing approach to cancer prevention, potentially overcoming irreversible genetic mutations in APC or β-catenin." (PMID 30131940, 2018). "For example, mutations in the adenomatous polyposis coli (APC) tumour suppressor gene or the gene encoding β-catenin (CTNNB1) result in colon adenomas and hypermethylation of SFRP1, a WNT antagonist, occurs frequently in colorectal cancer." (PMID 29316982, 2018). "Activation of Notch in APC+/1638N mutant mice, which spontaneously develop intestinal adenomas, was associated with higher tumor burden and worse survival." (PMID 30323897, 2018). "The reduction of APC mutations rate in TNM III+IV patients undermine its importance in Chinese patients tumor progression." (PMID 29937994, 2018). "In summary, our findings suggest that USP7 is a promising tumor-specific target for treatment of APC-mutated CRC by targeting pathological Wnt activation." (PMID 29045831, 2017). "Inactivation of USP7, either by CRISPR mutation or by small-molecule inhibitors, suppresses APC-mutated CRC tumor growth and Wnt activation by restoring β-catenin ubiquitination." (PMID 29045831, 2017). "Mutations in the MYD88, MET, and APC genes were found in tumor samples from 2 out of 11 patients who relapsed later, and none were found in patients without relapse (0/33) (p=0.054)." (PMID 28152507, 2017). "The central theme of this theory is the necessity of unstable chromosomes by the loss of APC function in the first stage and the accumulation of sequentially acquired mutations to exert tumor characteristics in a time-dependent manner." (PMID 29069792, 2017). "Our data highlight the potential of USP7 as a tumor-specific drug target for CRCs carrying CID-deleted APC mutations." (PMID 29045831, 2017). "Somatic mutations in the APC gene have been described in several tumour types such as pancreatic cancer, oral squamous-cell carcinoma and oesophageal cancer." (PMID 28576136, 2017). "Around 80% of tumours carry inactivating mutations in the APC gene, a key inhibitor of the WNT pathway." (PMID 28003334, 2017). "As an important integral part of the Wnt/β-catenin signaling pathway, the protein encoded by the APC gene plays key roles in tumor suppression by antagonizing the pathway." (PMID 29050326, 2017). "In the OMP-C8 PDX model, an APC mutated tumor, three cycles of anti-Rspo3 + nab-paclitaxel treatment dramatically reduced the cancer stem cell frequency by 40-fold, as assayed by the limiting dilution assay (LDA)." (PMID 29127379, 2017). "The adenomatous polyposis coli (APC) gene encodes a large multidomain protein and its dysfunction participates in tumor development." (PMID 28977861, 2017). "Region-specific APC mutations have been associated with distinct β-catenin transcriptional activity and tumor susceptibility." (PMID 29045831, 2017). "The tumour suppressor APC is a multifunctional protein implicated in intracellular localization of mRNAs and WNT signalling." (PMID 28134256, 2017). "The initial finding that RSPO fusions are mutually exclusive with APC mutations in human CRC implied that these events have redundant effects in tumour development." (PMID 28695896, 2017).
tumor (continued). "This argues against a selective pressure to lose PKM2 expression in promoting tumor growth following APC loss." (PMID 29214019, 2017). "PCR-based methods such as bead-based digital PCR in emulsions (BEAMing) and droplet-based digital PCR have been used to detect highly recurrent tumor-specific mutations in well-known driver genes such as APC, BRAF, KRAS and EGFR in plasma samples." (PMID 29156805, 2017). "Our current data indicate that USP7 is a potential tumor-specific drug target for APC-mutated CRCs by altering the Wnt signaling pathway." (PMID 29045831, 2017). "Instead, we showed that the tumor developed in concordance with the well-established two-hit genetic model for CRC wherein both APC gatekeeper alleles are mutated in a normal cell." (PMID 28561751, 2017). "In this study, we identified USP7 as a tumor-specific target by characterizing the fundamental Wnt-activating mechanism of APC mutation." (PMID 29045831, 2017). "With striking statistical significance (χ2P<1 × 10−15), tumours with two APC mutations had one mutation each from zones 1–3." (PMID 27302369, 2016). "ITF2 and APC methylation are significantly associated with tumor versus normal state (both P < 1.0×10-6)." (PMID 26884349, 2016). "Consistently, rodents fed n-3 PUFAs versus n−6 PUFAs or low-fat control diet controls showed a 20–50% reduction in tumor incidence induced by both APC mutation and carcinogens." (PMID 27769066, 2016). "In contrast, mutational activation of KRAS cannot initiate cancer in vivo, and only when combined with a mutation in APC mutant KRAS does promote tumor progression." (PMID 27276710, 2016). "Results show that β-catenin nuclear staining in APC single-mutation tumours was significantly stronger than APCwt tumours (Welch t-test P=0.014), indicating increased β-catenin activities in these APC-mutated tumours." (PMID 27302369, 2016). "In FAP and MAP we found that 50% of tumours carried somatic APC mutations (in the whole‐ and targeted‐exome experiments combined)." (PMID 26414517, 2016). "Taken together, KY1022 effectively inhibited APC and K-Ras mutation driven intra-tumor EMT and following tumor invasion in APCMin/+/K-RasG12DLA2 mice." (PMID 27835580, 2016). "Zones 1 (codons 1–218) and 4 (codons 1,588–2,843) had very few such mutations (N=3 for zone 1; N=2 for zone 4, both in one POLE tumour that also had two other APC-truncating mutations)." (PMID 27302369, 2016). "It has been reported that the expression of a dominant active PI3K synergizes with the loss of APC activity, resulting in dramatic changes in tumor multiplicity, size, morphology, and invasiveness." (PMID 27612425, 2016).
tumor (continued). "Previous studies have investigated the activation of VDR as well as LXR in APC-deficient mice and observed that the activity of both factors decreased tumor growth." (PMID 27092172, 2016). "As expected, RNF43 and ZNRF3 mutations tend to be mutually exclusive with APC and β-catenin mutations in those tumor types, reflecting their shared consequences in activating the Wnt/β-catenin signaling pathway." (PMID 27338477, 2016). "To interpret our observation on WNT activation in one-hit APC mutation tumours using the classic two-hit model of APC mutation in FAP, we considered several possible mechanisms as a ‘second hit'." (PMID 27302369, 2016). "APC gene mutations would cause regulatory function disorder, which is closely associated with occurrence and development of tumor." (PMID 27065015, 2016). "APC is now recognized as a recessive tumor suppressor gene, and inactivation of both alleles is necessary for tumor formation." (PMID 27507058, 2016). "As a tumor suppressor gene, APC inactive mutations are considered as the predominant mechanism attributing to β-catenin deregulation." (PMID 26760960, 2016). "Concurrently, it was found that the frequency of inactivating APC mutations remained constant as tumours progressed from benign to malignant stages." (PMID 27279102, 2016). "Tumor initiation is triggered by loss of the second APC allele which leads to constitutive activation of β-catenin." (PMID 27487143, 2016). "In this model, mutations of the adenomatous polyposis coli (APC) gene have been regarded as the earliest and the rate-limiting event of tumor initiation." (PMID 27589228, 2016). "Mono-colonization of mice that harbor a mutation in the adenomatous polyposis coli (APC) gene with an ETBF strain leads to high levels of fragilysin-dependent tumor formation in the gut." (PMID 27348220, 2016). "One tumor (patient P0027) had a complement of mutations in non-APC components (DKK1/2, CSKN1A1, and AXIN1) of the WNT pathway." (PMID 27245685, 2016). "Although Wnt/β-catenin signaling is known to be aberrantly activated in PDAC, mutations of CTNNB1, APC or other pathway components are rare in this tumor type, suggesting alternative mechanisms for Wnt/β-catenin activation." (PMID 25747895, 2015). "It remains to be shown if the p.P1369V missense mutation in the APC gene in tumor #3 results in enhanced activity of the β-catenin pathway." (PMID 26068980, 2015). "MUC2 deficient mice develop adenocarcinomas and when crossed with APC deficient mice, the result is accelerated tumor development and metastasis." (PMID 26230607, 2015). "Loss of the remaining wild type APC allele has often been implicated as the primary mechanism for increased β-catenin signaling leading to tumor development in APCMin/+ mice." (PMID 26500891, 2015). "It has been shown that mutation of the APC gene induces spontaneous development of tumours along the intestinal tract of rodents." (PMID 26561503, 2015).
tumor (continued). "The adenomatous polyposis coli (APC) gene serves as a tumor suppressor and its mutation forms the molecular basis of FAP." (PMID 26404250, 2015). "In gastrointestinal (GI) tumors, genes involved in APC-dependent (APC, Siah1, and Axin) targeting of β-catenin are often mutated, and similarly in APCMin/+ mice, tumor formation is mostly driven through inactivation of the wild type APC allele." (PMID 26500891, 2015). "The adenomatous polyposis coli (APC) gene is a tumor-suppressor gene that is implicated in both FAP and sporadic or familial colorectal carcinogenesis." (PMID 26311738, 2015). "Among other mechanisms, the major effector of the canonical Wnt pathway, β-catenin, is stabilized in tumors primarily via Wnt ligand overexpression, down-regulation of Wnt ligand antagonists, or loss of the APC tumor suppressor." (PMID 25658419, 2015). "There were no other common germ line variants identified within the region of the APC gene examined, suggesting that any effect from this region on tumour production is attributable to the c.3920T>A allele." (PMID 24416237, 2014). "It has been documented earlier also that PPARγ can act as a tumour promoter, only in the presence of APC mutation or aberrant Wnt signaling pathway which indeed is the observation in the current study." (PMID 24999478, 2014). "In fact, the association of the upregulated APC/C-dependent proteolysis profile with poor survival suggest this process is close linked to tumor progression." (PMID 24879114, 2014). "Ten variants were identified from eight genes in both the tumor and normal groups (APC, EGFR, FGFR3, KDR, MET, PDGFRA, RET and SMO)." (PMID 25404506, 2014). "This is especially relevant regarding the fact that most CC carry mutations in APC in all clonally derived tumor cells, suggestive of a constitutive and uniformly active WNT pathway in these tumors." (PMID 24930890, 2014). "This gene encodes the adenomatous polyposis coli (APC) protein, which is a well-characterized tumor suppressor regulating canonical Wnt signaling that is essential for tumorigenesis." (PMID 25238417, 2014). "Familial adenomatous polyposis is caused by mutations in the adenomatous polyposis coli (APC) gene, a tumour suppressor gene, located in the long arm of chromosome 5." (PMID 25326340, 2014). "In our study, we also found an increased population of tumor cells with APC mutations after chemoradiation in all three cases examined." (PMID 25275295, 2014). "In the remaining case, an APC mutation private to the primary tumor was likely lost in a chromosomal deletion in the paired metastasis." (PMID 25164765, 2014). "WNT6 and WNT11 encode Wnt ligands that have potential tumor-promoting roles even in CRCs with APC mutations and that have the capability to signal to the stromal components to modulate the tumor microenvironment." (PMID 24651522, 2014). "Our study provides strong evidence for a correlation between progressive hypermethylation and silencing of several Wnt antagonists with stepping-up in Wnt pathway activity beyond the APC loss associated tumour-initiating Wnt signalling levels." (PMID 25432628, 2014). "Although 11 of the 23 tumours had acquired somatic APC mutations, all in the c.3920T>A allele, only 6 of these tumours (26%) had acquired a somatic mutation by slippage of the A8 tract." (PMID 24416237, 2014). "It will also be important to determine if there are distinct consequences of APC mutation and down-regulation on cell motility and tumor progression, which differ in frequency among tumor types." (PMID 23302090, 2013). "The adenomatous polyposis coli (APC) tumour suppressor gene encodes a 2843 residue (310 kDa) protein." (PMID 24156781, 2013). "As far as we are aware, this work is the first to address the role of these protrusion-associated APC/β-catenin complexes in tumor cells." (PMID 23302090, 2013).
tumor (continued). "The APC tumor suppressor is mutated or downregulated in many tumor types, and is prominently localized to punctate clusters at protrusion tips in migratory cells, such as in astrocytes where it has been implicated in directed cell motility." (PMID 23302090, 2013). "The APC gene is mutated in the vast majority of colon cancers and a significant proportion of other tumours." (PMID 23840886, 2013). "Despite these findings, it is not clear how this pool of APC, and its role at the leading edge and at membrane protrusions in migration, contributes to tumor suppression mediated by APC and drives tumor initiation or progression when APC is mutated." (PMID 23302090, 2013). "Based on these findings, we postulated that IM in the stomach enhances the risk of tumor development by increasing the Lgr5+ cell population, which is highly susceptible to transformation by APC mutation." (PMID 24340024, 2013). "Concomitantly, we exclude characteristic activating mutations in the APC or β-catenin gene as a cause for cytoplasmic β-catenin stabilization, as they frequently occur in other tumour entities." (PMID 22919349, 2012). "The majority of colorectal carcinomas carry inactivating mutations in the Adenomatous polyposis coli (APC) tumor suppressor which lead to stabilization of β-Catenin, mimicking Wnt stimulation." (PMID 22685558, 2012). "It has a chemically-induced dominant mutation (base substitution mutation) in the adenomatous polyposis coli (APC) gene which is considered a tumor suppressor gene." (PMID 22284906, 2012). "Overall, 71 tumours (68.9%) had the APC gene mutated: 45 CRCs had 1 deleterious mutation, 23 had 2 mutations, 2 had 3 mutations and 1 had 6 mutations." (PMID 21901162, 2011). "Most cases of sporadic tumours are associated with somatic mutations in genes coding for β-catenin or APC, whereas familial cases are associated with germline mutations in the APC gene." (PMID 21468052, 2011). "The adenomatous polyposis coli (APC) gene is thought to play a gate-keeping role in the tumor formation and progression and is the most commonly mutated gene in all colorectal cancers." (PMID 22168384, 2011). "APC encodes a tumor suppressor protein that acts as an antagonist of the Wnt signaling pathway and is involved in other processes such as cell migration and adhesion." (PMID 22051105, 2011). "Of 43 tumours with only one deleterious APC mutation, 27 had LOH (62.8%), while of 20 tumours with 2 and more mutations, only 1 had LOH (5%, P<0.0001)." (PMID 21901162, 2011). "Although Wnt signaling is aberrantly activated in PDAC, mutations of CTNNB1, APC or other pathway components are rare in this tumor type suggesting alternative mechanisms for Wnt activation." (PMID 21811562, 2011). "Mutant allele specific amplification was possible in 12 of 26 tumours with 2 and more APC mutations to show their phase." (PMID 21901162, 2011). "The ApcMin/+ mouse is a well-established model of FAP with a germline mutation in one APC allele, thus increasing the probability of a double allele mutation and tumor formation." (PMID 22168384, 2011). "Of the total of 31 APC mutations in MSI tumours, 15 were FS (48.4%) and 16 point substitutions (51.6%)." (PMID 21901162, 2011). "Interfering with c-Myc levels in mouse models with APC mutations rescued the observed phenotypes, leading to a reduction in tumor burden and increased survival." (PMID 19785743, 2009).